NPC1 (NPC intracellular cholesterol transporter 1)
Diseases named in the same sentence as NPC1 in open-access papers (continued):
Sharing a sentence is not in itself a finding about the gene and the disease.
tumor (continued). "This knockdown significantly inhibited cell migration, though it did not affect cell proliferation or tumor growth in xenograft models, indicating that NPC1-driven migration depends on TGFBR1." (PMID 39762312, 2025). "Tumor inflammation (r = −0.094, p = 0.135) and fibrosis stages (r = 0.035, p = 0.578) did not correlate with NPC1 protein levels." (PMID 40722778, 2025). "To further investigate the prognostic value of NPC1 in HCCs, we performed a tissue microarray (TMA)-based immunohistochemistry (IHC) study of NPC1 in HCC tumor and paired non-tumor liver tissues." (PMID 39762312, 2025). "NPC1 protein was higher in female patients with tumor stage pT4 compared to pT3 and pT2 but was not related to grading (p = 0.776)." (PMID 40722778, 2025). "While interfering with NPC1 in vitro does not affect tumor cell growth, interference in vivo significantly inhibits tumor growth." (PMID 39707615, 2025). "To better understand the contribution of these GBM cell-states within our Q-Cell resource, we firstly analysed 257 unique genes, separating tumours into six metamodules (MES1-, MES2-, NPC1-, NPC2-, OPC-, and AC-like) as per Suva and colleagues encompassing each of the identified four cell-states." (PMID 31973233, 2020). "All of these cell lines are derived from males, and, to our knowledge, whether cells from female patients have increased proliferation upon NPC1 overexpression, consistent with its positive correlation with tumor size in females, has not been investigated." (PMID 40722778, 2025). "NPC1 protein in the HCC tissues positively correlated with the UICC score (r = 0.170, p = 0.006) but not with tumor size (r = 0.035, p = 0.578)." (PMID 40722778, 2025). "We injected luciferase-expressing negative control (sgNC) or NPC1-depleted (sgNPC1) ARP-1 cells into NSG mice via the tail vein and monitored tumor growth." (PMID 41013744, 2025). "NPC1 protein in the HCC tissues positively correlated with the UICC score (r = 0.196, p < 0.001) but not with tumor size (r = 0.092, p = 0.100)." (PMID 40722778, 2025). "In males, NPC1 protein in the non-HCC tissues was not related to T stage, lymph node invasion, grading, tumor size, and UICC scores (p > 0.05 for all)." (PMID 40722778, 2025).
metabolic disease (10 papers, 2015 to 2025). A congenital disorder (due to inherited enzyme abnormality) or acquired (due to failure of a metabolically important organ) disorder resulting from an abnormal metabolic process. "Niemann–Pick disease (NP) type C is an autosomal recessive metabolic disorder caused by mutations in the NPC1 or NPC2 gene." (PMID 37458497, 2023). "Additionally, NPC1 gene variants are implicated in different common metabolic disorders, an observation that can be explained using NPC1 protein influence on steroid hormone production and/or lipid homeostasis." (PMID 37892989, 2023). "Other top associations for BF%-HF were NPC1 gene variations, which might lead to metabolic diseases by modulating steroid hormone synthesis and lipid homeostasis." (PMID 33910581, 2021). "The race/ethnic dependent linkage-disequilibrium of these four NPC1 polymorphisms may also account for the contrasting associations observed for metabolic disease phenotypes as presented in the next section." (PMID 26120596, 2015). "The objectives for this prospective cross-sectional study were to determine allele frequencies for NPC1 polymorphisms (644A>G, 1926C>G, 2572A>G, and 3797G>A) and association with metabolic disease phenotypes in an ethnically diverse New Mexican obstetric population." (PMID 26120596, 2015). "NPC1 (Npc1nih) and Sandhoff (Hexb−/−) mutant mice recapitulate many features of the corresponding human disorders, including rapid onset of metabolic disease, excessive neuronal storage, and progressive motor and cognitive pathology." (PMID 26467605, 2016). "Moreover, the significant linkage-disequilibrium between each of the four coding non-synonymous NPC1 polymorphisms may be responsible for cooperatively altering NPC1 protein structure and adversely affecting function that predisposes to different metabolic disease phenotypes." (PMID 26120596, 2015).
genetic disease (9 papers, 2016 to 2025). "Mutations on human genes encoding AAT 19, collagen α−1(II) chain (COL2A1) 20, Niemann-Pick type C1 (NPC1) 21, and dysferlin (DYSF) 22, 23 can cause their misfolding in the ER, leading to degradation by ERQC and various genetic diseases." (PMID 40678220, 2025). "NPC1 is a genetic disorder that affects the transport of LDL-derived cholesterol from the lumen to the membrane of the lysosome." (PMID 37367064, 2023). "The Niemann-Pick type C1 (NPC1) is a rare genetic disease characterized by the accumulation of endocytosed cholesterol and other lipids in the endosome/lysosome compartments." (PMID 31178699, 2019). "Engineered NPC1 mRNA with optimized codons and N1-methylpseudouridine base modification has been demonstrated to correct the cholesterol transport defect in NP-C1 patient cells, confirming the promising potential of engineered mRNA in the treatment of inherited disease." (PMID 39263569, 2024). "However, we cannot exclude the direct action of genistein on the mutant protein NPC1 in NPC1 fibroblasts, which could enhance its residual activity as has previously been described for other mutant proteins in genetic diseases, such as CF and MPS." (PMID 33921734, 2021). "Consequently, the absence of either NPC1 or NPC2 protein could lead to the manifestation of this genetic disease, as there are no substitutes for these two proteins in NP-C1." (PMID 39263569, 2024).
autosomal recessive inherited disease (2 papers, 2016 to 2021). "It is an autosomal recessive inherited disease that results from mutations in the NPC1 or NPC2 genes." (PMID 34596813, 2021). "Niemann-Pick Type C1 (NPC1) is an autosomal recessive inherited disorder characterized by accumulation of cholesterol and glycosphingolipids." (PMID 27834854, 2016).
bacterial infection (2 papers, 2012 to 2024). "We further established elevation of innate immunity in Npc1−/− mice through multiple functional assays including inhibition of bacterial infection as well as cellular analysis and immunohistochemistry." (PMID 23094108, 2012). "Little is known about the role of NPC1 in bacterial infections." (PMID 38696518, 2024).
cardiovascular disease (2 papers, 2013 to 2022). "It has been reported that Niemann-Pick type C1 (NPC1) gene mutations might be related to cardiovascular diseases." (PMID 35480314, 2022).
Endocrine disorders (1 paper, 2019). "Endocrine disorders are not the focus of research on human NPC1 mutations, and the few available data refer mostly to Npc1 mouse models." (PMID 31500175, 2019).
hematological disorders (1 paper, 2021). "Since NPC1 and hematological disorders were excluded, sea blue histiocytes could be explained by enhanced creation of ceroid lipofuscin concentrating in macrophages." (PMID 34168672, 2021).
intestinal disease (1 paper, 2022). "The improvement in intestinal disease activity in NPC1 patients was associated with reduced pain, perianal disease and improved nutritional status." (PMID 35694196, 2022).
neurodevelopmental disorder (1 paper, 2023). A behavioral and cognitive disorder with onset during the developmental period that involves impaired or aberrant development of intellectual, motor, or social functions. "Although SLOS and CTD are neurodevelopmental disorders, unlike NPC1, neurodegeneration is not observed in either SLOS or CTD." (PMID 36721240, 2023).
NPC1 also shares sentences with these, for which no sentence is quoted: cerebellar ataxia (7 papers); type 2 diabetes (4); Dystonia (3); Thrombocytopenia (3); cardiac disease (2); colitis (2); coronary atherosclerosis (2); developmental delay (2); gastric cancer (2); glioblastoma (2); influenza (2); intestinal inflammation (2); Multiple sulfatase deficiency (2); Onset (2); progressive supranuclear palsy (2); renal cell carcinoma (2); Spastic paraplegia (2); tuberculosis (2); Wilson disease (2); Abdominal obesity (1); abetalipoproteinemia (1); acquired immune deficiency syndrome (1); acute liver failure (1); Adult onset (1); alcoholic liver cirrhosis (1); axonal neuropathy (1); Bladder carcinoma (1); Canavan disease (1); ceroid lipofuscinoses (1); cervical squamous cell carcinoma (1).
A further 77 diseases each share a sentence with NPC1 in 1 paper.